MAP3K19 (mitogen-activated protein kinase kinase kinase 19)
Synonyms: RCK; YSK4; FLJ23074
Tractability: Small molecule: a high-quality ligand is known; it belongs to a druggable protein family. PROTAC: ubiquitination databases record sites on it; a small molecule that binds it is known.
Target class: Enzyme; STE protein kinase STE11 family; Kinase; STE protein kinase group; Protein Kinase
Gene: Protein-coding gene on chromosome 2 (134,964,485 to 135,047,468, reverse strand). Ensembl gene ENSG00000176601.
Subcellular location (Human Protein Atlas): Cytosol
Gene Ontology:
Molecular function: ATP binding; protein kinase activity; protein serine kinase activity; protein serine/threonine kinase activity
Biological process: intracellular signal transduction
Genetic constraint (gnomAD): Loss-of-function variants: 75 observed, 94.61 expected, observed/expected ratio (o/e) 0.79, 90% interval 0.66 to 0.96. The upper end of that interval is the gene's LOEUF score, 0.96, which puts it in group 4 of 6, group 1 being the genes least tolerant of losing a copy. Missense variants: 1,317 observed, 1,471.5 expected, observed/expected ratio (o/e) 0.89, 90% interval 0.85 to 0.94. Synonymous variants: 469 observed, 504.46 expected, observed/expected ratio (o/e) 0.93, 90% interval 0.86 to 1.
Homologues: Orthologues: chimpanzee MAP3K19 (98% identical), macaque MAP3K19 (91% identical), pig MAP3K19 (75% identical), dog MAP3K19 (74% identical), rabbit MAP3K19 (71% identical), guinea pig MAP3K19 (69% identical), mouse Map3k19 (59% identical), rat Map3k19 (58% identical), tropical clawed frog map3k19 (24% identical), zebrafish map3k19 (15% identical), Caenorhabditis elegans drl-1 (7% identical). Paralogues in human: MAP3K1 (17% identical), PAK2 (11% identical), PAK3 (11% identical), PAK6 (11% identical), PAK1 (11% identical), PAK5 (10% identical), PAK4 (10% identical), MAP3K14 (8% identical), MAP4K3 (8% identical), MAP4K4 (8% identical), MAP4K5 (8% identical), STK26 (8% identical), and 23 more.
Diseases named in the same sentence as MAP3K19 in open-access papers:
MAP3K19 is named in the same sentence as 18 diseases in open-access papers, as found by Europe PMC text mining. Sharing a sentence is not in itself a finding about the gene and the disease. The quoted sentences say what the papers report.
pulmonary fibrosis (6 papers, 2016 to 2024). Chronic progressive interstitial lung disorder characterized by the replacement of the lung tissue by connective tissue, leading to progressive dyspnea, respiratory failure, or right heart failure. "MAP3K19, found in bronchial epithelial cells, type II pneumocytes, and lung macrophages, is implicated in pulmonary fibrosis and chronic obstructive pulmonary disease (COPD)." (PMID 38575860, 2024). "Inhibiting MAP3K19 in mice models has shown a reduction in fibrosis and collagen deposition, thus preventing pulmonary fibrosis." (PMID 38575860, 2024). "This regulatory process resembles the MAP3K19-induced inhibition of lung fibrosis, indicating potential regulatory overlaps in marine mammal lung fibrosis." (PMID 38575860, 2024). "MAP3K19 inhibition by siRNA also attenuated the profibrotic activity of cultured fibroblasts in an adoptive transfer mouse model of pulmonary fibrosis." (PMID 37445830, 2023). "Studies demonstrated that MAP3K19 expression is elevated in idiopathic pulmonary fibrosis (IPF) tissues." (PMID 37445830, 2023). "MAP3K19 inhibition by a siRNA inhibitor significantly attenuated pulmonary fibrosis in a bleomycin-induced murine model." (PMID 37445830, 2023). "At the same time, MAP3K19 significantly attenuated bleomycin-induced pulmonary fibrosis and is a central mediator of cigarette smoke-induced pulmonary inflammation and lower airway destruction." (PMID 36439693, 2022). "Quantitative protein and biochemical assays, as well as histological analysis, showed that MAP3K19 was required for the development of lung fibrosis in SCID mice humanized with IPF lung fibroblasts." (PMID 31875033, 2019). "Together, these data demonstrated that targeting MAP3K19 using a small-molecule approach therapeutically reduced pulmonary fibrosis in a humanized C.B-17SCID/bg mouse model of IPF." (PMID 31875033, 2019). "Mice treated with the MAP3K19 inhibitor or dexamethasone had significantly reduced pulmonary fibrosis, collagen deposition and lung collagen content." (PMID 27144281, 2016). "Thus, the therapeutic targeting of human MAP3K19 via a siRNA approach significantly reduced pulmonary fibrosis as assessed both using biochemical and transcript analysis approaches in a humanized C.B-17SCID/bg model of IPF." (PMID 31875033, 2019). "We next wanted to investigate whether MAP3K19 inhibition could act therapeutically in this model of pulmonary fibrosis." (PMID 27144281, 2016). "Finally, in an animal model of IPF, inhibition of MAP3K19 strongly attenuated bleomycin-induced pulmonary fibrosis when administered either prophylactically ortherapeutically." (PMID 27144281, 2016). "Taken together, these results demonstrate that inhibition of MAP3K19 significantly attenuated the development of pulmonary fibrosis in a murine bleomycin model, and these effects may be attributable, at least in part, to inhibition of the TGF-β pathway." (PMID 27144281, 2016). "A few other studies have further shown that MAP3K19 inhibition attenuated the profibrotic activity of these cells in vitro and in an adoptive transfer severe combined immunodeficiency (SCID) model of pulmonary fibrosis." (PMID 37998736, 2023). "Thus, MAP3K19 may be a promising therapeutic target for idiopathic pulmonary fibrosis." (PMID 37445830, 2023). "In studies on lung cancer, targeting MAP3K19 has been reported to prevent human lung myofibroblast activation in vitro and in a humanized SCID model of idiopathic pulmonary fibrosis." (PMID 36439693, 2022). "Targeting MAP3K19 both in vitro and in vivo markedly altered IPF fibroblast to myofibroblast differentiation and the maintenance of pulmonary fibrosis in C.B-17SCID/bg humanized with IPF fibroblasts." (PMID 31875033, 2019). "We investigated the role of a novel kinase, MAP3K19, upregulated in IPF tissue, in TGF-β-induced signal transduction and in bleomycin-induced pulmonary fibrosis." (PMID 27144281, 2016).
pulmonary fibrosis (continued). "MAP3K19 was required for IPF myofibroblast differentiation, and targeting its activity attenuated the profibrotic activity of these cells both in vitro and in an adoptive transfer SCID model of pulmonary fibrosis." (PMID 31875033, 2019). "Finally, antagonism of MAP3K19 by a small molecule inhibitor, or siRNA, can inhibit TGF-β signaling and target gene transcription as well as potently diminish bleomycin-induced lung fibrosis in a murine model of IPF." (PMID 27144281, 2016).
chronic obstructive pulmonary disease (3 papers, 2023 to 2024). A chronic and progressive lung disorder characterized by the loss of elasticity of the bronchial tree and the air sacs, destruction of the air sacs wall, thickening of the bronchial wall, and mucous accumulation in the bronchial tree. "Moreover, MAP3K19 expression is increased in chronic obstructive pulmonary disease." (PMID 37445830, 2023). "Among these components, MAP3-kinase 19 (MAP3K19), also known as YSK4 and RCK (regulated in the chronic obstructive pulmonary disease (COPD) kinase), is a newly discovered MAP kinase kinase kinase present in humans and mice." (PMID 37998736, 2023).
lung carcinoma (3 papers, 2022 to 2023). "Recent findings indicate that MAP3K19 activates ERK and JNK kinases, therefore enhancing the viability of mutant lung cancer cells." (PMID 37375208, 2023).
asthma (1 paper, 2023). "We also evaluated the involvement of MAP3K19 in the OVA-induced asthma murine model using Map3k19-deficient (MAP3K19−/−) mice." (PMID 37998736, 2023). "We also investigated whether MAP3K19 knockdown attenuated the airway inflammation in Map3k19-deficient (MAP3K19−/−) mice using the OVA-induced asthma murine model." (PMID 37998736, 2023). "The mitogen-activated protein kinase (MAPK) signaling pathway is involved in the epithelial–mesenchymal transition (EMT) and asthma; however, the role of mitogen-activated protein kinase kinase kinase 19 (MAP3K19) remains uncertain." (PMID 37998736, 2023). "Similarly, in our mouse experiments, we observed increased RANTES production in an asthma model of MAP3K19−/− mice, whereas the increased TSLP- and TWEAK-expressing cells in the MAP3K19−/− mice were no different from those of the wild type." (PMID 37998736, 2023). "Our in vitro studies suggested that MAP3K19 is involved in type 2 inflammation and cellular EMT processes that may contribute to airway inflammation in patients with asthma; therefore, we investigated whether MAP3K19 knockout is involved in airway inflammation in a murine model of asthma." (PMID 37998736, 2023). "Consequently, the MAP3K19 kinase function remains unclear, and our findings indicating that MAP3K19 inhibition exacerbates asthma will shed further light on this topic." (PMID 37998736, 2023). "Furthermore, the expression of MAP3K19 mRNA was upregulated in both the lungs and tracheas of the mice in the OVA-induced asthma murine model." (PMID 37998736, 2023). "We hypothesized that MAP3K19 is involved in downstream TWEAK stimulation and airway inflammation in patients with asthma because TWEAK can activate NF-κB and enhance the TGF-β1-induced EMT." (PMID 37998736, 2023). "Therefore, we investigated the involvement of MAP3K19 in in vitro EMT and ovalbumin (OVA)-induced asthma murine models." (PMID 37998736, 2023). "Finally, we could not sufficiently analyze the asthma model using MAP3K19 knockout mice, and further studies are required to determine how non-Smad signaling pathways, such as the NF-κB and MAPK pathways and MKP-1, are involved in these knockout mice." (PMID 37998736, 2023). "However, the MAP3K19 kinase still has the lowest number of publications available in the MAP3K family, its function has not been determined, and its role in airway inflammation, including asthma, remains unclear." (PMID 37998736, 2023). "Fourth, we could not determine the optimal protocol of the OVA-induced asthma murine model to clarify the involvement of the EMT and the worsened eosinophilic airway inflammation effects of the MAP3K19 knockout mice." (PMID 37998736, 2023).
cervical cancer (1 paper, 2023). A primary or metastatic malignant neoplasm involving the cervix. "Previous in vitro culture systems have shown that MAP3K19 siRNA or MAP3K19 inhibitors reduced the TGF-β-induced phospho-Smad2/3 nuclear translocation in an A549 human lung adenocarcinoma cell line, THP-1 human monocytes/macrophages, Human Embryonic Kidney cells, and HeLa cervical cancer cells." (PMID 37998736, 2023).
chronic lung disease (1 paper, 2019). According to the definitions of the American and British Thoracic Societies, including pulmonary functional tests, X-rays, and CT scans for items such as fibrosis, bronchiectasis, bullae, emphysema, nodular or lymphomatous abnormalities. "MAP3K19 is unique in that it is highly specific to the lung and it is uniquely upregulated in chronic lung diseases with abnormal remodeling." (PMID 31875033, 2019).
COVID-19 (1 paper, 2024). A disease caused by infection with severe acute respiratory syndrome coronavirus 2. "Regarding single-cell expression analysis for MAP3K19, COVID19_GWAS_Aanlyzer will employ several SAS macros to visualize the specific expression of MAP3K19 in ciliated cell types across different samples, such as healthy controls, severe COVID-19 patients, and critical COVID-19 patients." (PMID 39088323, 2024).
head and neck cancer (1 paper, 2023). A primary or metastatic malignant neoplasm affecting the head and neck. "The mutations in various genes, such as PCDHA3 and MAP3K19, altered the expression of C19orf80 in head and neck cancer patients." (PMID 37375208, 2023).
influenza infection (1 paper, 2016). "We assessed the effect of MAP3K19 inhibition on various parameters in a murine model of influenza infection following cigarette smoke exposure." (PMID 27935962, 2016).
ovarian carcinoma (1 paper, 2023). A malignant neoplasm originating from the surface ovarian epithelium. "The present study demonstrated that mitogen-activated protein three kinase 19 (MAP3K19) was the key CCL2 target for regulating ovarian cancer progression through transcriptome sequencing." (PMID 37445830, 2023). "To explore the biological roles of MAP3K19 in the proliferation, migration, and invasion of ovarian cancer cells, we subsequently knocked out MAP3K19 in the A2780 cells." (PMID 37445830, 2023). "Transcriptome sequencing demonstrated that MAP3K19 was the key target for CCL2 in regulating ovarian cancer progression." (PMID 37445830, 2023). "CCL2 significantly promoted the proliferation, migration, and invasion of ovarian cancer cells by targeting MAP3K19." (PMID 37445830, 2023). "MAP3K19 was the key target for CCL2 in the regulation of ovarian cancer progression." (PMID 37445830, 2023). "MAP3K19 knockout inhibited ovarian cancer cell proliferation, migration, and invasion." (PMID 37445830, 2023). "Thus, MAP3K19 knockout inhibited the proliferation, migration, and invasion of ovarian cancer cells." (PMID 37445830, 2023). "Additionally, mitogen-activated protein three kinase 19 (MAP3K19) was the key target for CCL2 to regulate ovarian cancer progression." (PMID 37445830, 2023). "Additionally, MAP3K19 knockout inhibited ovarian cancer cell proliferation, migration, and invasion." (PMID 37445830, 2023). "Moreover, MAP3K19 knockout inhibited the biological activity of ovarian cancer cells." (PMID 37445830, 2023). "Moreover, MAP3K19 knockout inhibited the biological functions of ovarian cancer cells." (PMID 37445830, 2023). "MAP3K19 knockout inhibited the biological functions of ovarian cancer cells, and thus, it may be the critical target of CCL2 in the regulation of ovarian cancer development." (PMID 37445830, 2023).
cancer (3 papers, 2022 to 2023). A tumor composed of atypical neoplastic, often pleomorphic cells that invade other tissues. "MAP3K19 inhibition is crucial for the survival of Kras mutant cancers, which inactivates the extracellular regulated protein kinase and c-jun N-terminal kinase pathways." (PMID 37445830, 2023). "The infiltration abundance of immune cells was analyzed by CIBERSORT, and the correlation heatmap in pan-cancer showed that MAP3K19 and NTSR1 were significantly correlated with immune infiltration in more types of tumors." (PMID 36439693, 2022). "Subsequently, further immune score, stromal score, and ESTIMATE score in the pan-cancer TME revealed the potential roles of MAP3K19 and NTSR1 in regulating stromal/immune scores and gene expression in tumors." (PMID 36439693, 2022). "ESTIMATE analysis results of pan-cancer species analysis of MAP3K19 and NTSR1 in TCGA database." (PMID 36439693, 2022). "In our study, the use of RNA-seq data as well as global proteomic data inferred MAP3K19 and NTSR1 for pan-cancer tumor purity, immune score, and stromal score." (PMID 36439693, 2022). "Previous in vitro studies have shown that MAP3K19 activated the ERK and JNK signaling pathways in vitro kinase assays and that MAP3K19 expression plasmid transiently transfected and activated the ERK and JNK pathways in cancer cell lines." (PMID 37998736, 2023).
infection (1 paper, 2021). The state of being infected such as from the introduction of a foreign agent such as serum, vaccine, antigenic substance or organism. "Studies have begun to identify host specific pathways and factors that are involved in CS induced infection pathogenesis, such as CCR2, IL-17 and MAP3K19, and thus represent exciting immediate potential therapeutic targets for treatment." (PMID 34959590, 2021).
tumor (1 paper, 2022). "We included clinical factors including age at diagnosis, gender, tumor pathological grade, lymph node status, distant metastasis, TNM stage, and gene signatures MAP3K19 and NTSR1 expression (high- and low-expression groups divided by median value)." (PMID 36439693, 2022). "The abundances of 22 tumor-infiltrating immune compartments in LUAD samples were systematically recorded by the CIBERSORT algorithm and integrated with MAP3K19 and NTSR1 molecular profiles to analyze the degree of immune infiltration in LUAD." (PMID 36439693, 2022).
MAP3K19 also shares sentences with these, for which no sentence is quoted: idiopathic pulmonary fibrosis (3 papers); emphysema (1); lung adenocarcinoma (1); Lung Injury (1); pancreatic cancer (1).